PHF23 (PHD finger protein 23)
Description:
Acts as a negative regulator of autophagy, through promoting ubiquitination and degradation of LRSAM1, an E3 ubiquitin ligase that promotes autophagy in response to starvation or infecting bacteria.
Synonyms: MGC2941; FLJ16355; hJUNE-1b
Tractability: PROTAC: ubiquitination databases record sites on it; its protein half-life has been measured.
Target class: Plant homeodomain; Epigenetic regulator; Reader
Gene: Protein-coding gene on chromosome 17 (7,235,029 to 7,239,722, reverse strand). Ensembl gene ENSG00000040633.
Subcellular location: Nucleus; Cytoplasm
Subcellular location (Human Protein Atlas): Nucleoplasm; Cytosol
Gene Ontology:
Molecular function: protein binding
Biological process: negative regulation of autophagosome assembly; negative regulation of autophagosome maturation; positive regulation of protein ubiquitination
Cellular component: cytoplasm; cytosol; nucleoplasm; nucleus
Genetic constraint (gnomAD): Loss-of-function variants: 2 observed, 35.75 expected, observed/expected ratio (o/e) 0.0559, 90% interval 0.022 to 0.18. The upper end of that interval is the gene's LOEUF score, 0.18, which puts it in group 1 of 6, group 1 being the genes least tolerant of losing a copy. Missense variants: 456 observed, 523.94 expected, observed/expected ratio (o/e) 0.87, 90% interval 0.81 to 0.94. Synonymous variants: 234 observed, 198.72 expected, observed/expected ratio (o/e) 1.18, 90% interval 1.06 to 1.31.
Homologues: Orthologues: chimpanzee PHF23 (99% identical), macaque PHF23 (99% identical), dog PHF23 (96% identical), rabbit PHF23 (96% identical), pig PHF23 (95% identical), mouse Phf23 (94% identical), rat Phf23 (91% identical), guinea pig PHF23 (82% identical), tropical clawed frog phf23 (37% identical), zebrafish phf23b (37% identical), zebrafish phf23a (33% identical). Paralogues in human: PHF13 (29% identical).
Diseases named in the same sentence as PHF23 in open-access papers:
PHF23 is named in the same sentence as 14 diseases in open-access papers, as found by Europe PMC text mining. Sharing a sentence is not in itself a finding about the gene and the disease. The quoted sentences say what the papers report.
acute myeloid leukemia (7 papers, 2015 to 2024). Acute myeloid leukemia (AML) is a group of neoplasms arising from precursor cells committed to the myeloid cell-line differentiation. "PHD fingers have been shown to play a critical role in oncogenic drivers; for example, a chromosomal translocation in the PHD finger of PHF23 or lysine (K)-specific demethylase 5A (KDM5A) was implicated in acute myeloid leukemia." (PMID 28055972, 2017). "Previous studies have reported that NUP98 fused with PHF23 to form NP23, which plays an important role in acute myeloid leukemia and is closely associated with disease onset and evolution." (PMID 37626047, 2023).
leukemia (4 papers, 2019 to 2025). A malignant (clonal) hematologic disorder, involving hematopoietic stem cells and characterized by the presence of primitive or atypical myeloid or lymphoid cells in the bone marrow and the blood. "Beyond AML, PHF23 contributes to the pathogenesis of other leukemias." (PMID 41268576, 2025).
lung carcinoma (3 papers, 2023 to 2025). "Given the correlation between PHF23 and tumor size and lymph node metastasis, we hypothesized that PHF23 might also be associated with cell proliferation and migration in lung cancer cells." (PMID 37626047, 2023). "Hence, exploring whether the effect of PHF23 on ACTN4 protein stability is implicated in the resistance process to EGFR-TKIs could provide a new target for combating drug resistance in lung cancer." (PMID 37626047, 2023). "CCK8 assays, colony formation tests, and EDU labeling consistently showed that elevated PHF23 expression enhances lung cancer cell proliferation by accelerating G1/S phase transition." (PMID 41268576, 2025). "A comprehensive analysis of lung cancer samples from TCGA revealed that upregulation of PHF23 increased the 50% inhibitory concentration (IC50) of cisplatin and docetaxel, two commonly used drugs for chemotherapy in NSCLC." (PMID 37626047, 2023). "Western blot assays of clinical lung cancer tissues and paraneoplastic tissues showed that PHF23 protein was significantly higher in tumors than in paraneoplastic tissues." (PMID 37626047, 2023). "Conversely, knockdown of PHF23 inhibited the proliferation, G1/S transition, and migration of lung cancer cells." (PMID 37626047, 2023). "Immunohistochemical experiments revealed that PHF23 protein was highly expressed in lung cancer tissues and weakly expressed in normal bronchial epithelial and alveolar tissues." (PMID 37626047, 2023). "Consistently, our experiments suggested that the knockdown of ACTN4 partially abrogates the role of PHF23 in promoting chemoresistance in lung cancer." (PMID 37626047, 2023). "In this study, we demonstrate that PHF23 acts as a pro-oncogene, promoting proliferation, migration and drug resistance in lung cancer." (PMID 37626047, 2023). "In addition, PHF23 also enhanced the migratory ability of lung cancer cells by upregulating the expression of MMP2, MMP9, and N-Cadherin while downregulating the expression of E-Cadherin." (PMID 41268576, 2025). "Interestingly, a recent study presented a similar regulatory mechanism in lung cancer, where plant homologous structural domain finger protein 23 (PHF23) enhanced the stability of alpha-actinin-4 (ACTN4) by inhibiting its interaction with E3 ligase." (PMID 39414762, 2024). "In our study, we identified PHF23 as a potential therapeutic target for lung cancer chemotherapy." (PMID 37626047, 2023). "To further investigate the expression of PHF23 in NSCLC cells, we examined multiple lung cancer cell lines and found that PHF23 was highly expressed in multiple lung cancer cell lines except for the NCI-H460 cell line, compared with normal bronchial epithelial HBE cells." (PMID 37626047, 2023). "We hypothesized that PHF23 in lung cancer cells functions through the PHD in cell biological processes." (PMID 37626047, 2023). "This suggests that PHF23 may be involved in the development of chemoresistance in lung cancer." (PMID 37626047, 2023). "In vitro growth of lung cancer cells was assessed by CCK8, colony formation, and EDU incorporation assays, which revealed that strong expression of PHF23 promoted high proliferation of lung cancer cells." (PMID 37626047, 2023). "We constructed a mutant plasmid with knockout of the PHD in PHF23 and found that PHF23 binds to ACTN4 via the PHD and inhibits the ubiquitination level of ACTN4, thereby promoting malignant biological behaviors of lung cancer cells." (PMID 37626047, 2023). "Then, we experimentally verified that PHF23 activates the ERK signaling pathway by stabilizing ACTN4, thereby promoting proliferation, migration, and chemoresistance of lung cancer cells in vitro and in vivo." (PMID 37626047, 2023).
degenerative joint diseases (2 papers, 2023 to 2025). "Additionally, PHF23 is associated with various diseases including various malignancies, osteoarthritis, and tuberculosis, all of which currently lack effective and targeted treatment options." (PMID 41268576, 2025).
breast carcinoma (1 paper, 2017). "In contrast, the most deleted gene, PHF23, had the highest frequency (43.48%) of mRNA underexpression (Z-score < -1), and CHD3 was underexpressed in 35.14% of TCGA breast cancer samples." (PMID 28055972, 2017).
glioma (1 paper, 2026). A benign or malignant brain and spinal cord tumor that arises from glial cells (astrocytes, oligodendrocytes, ependymal cells). "Our results identify PHF23 as a critical oncogenic driver in glioma and support the PHF23-RPS for risk stratification." (PMID 41898439, 2026). "Functional assays, including in vitro experiments and in vivo experiments via a male BALB/c nude mouse orthotopic glioma model (n = 6/group), confirmed that PHF23 silencing inhibited glioma malignancy." (PMID 41898439, 2026). "Our analysis revealed significant upregulation of PHF23 in high-grade gliomas, while the PHF23-RPS exhibited strong predictive performance (AUC = 0.853)." (PMID 41898439, 2026). "In this study, the Chinese Glioma Genome Atlas (CGGA-325/693) and The Cancer Genome Atlas (TCGA-LGG/GBM) cohorts were used to explore the pathological role of PHD finger protein 23 (PHF23) in gliomas." (PMID 41898439, 2026).
lung adenocarcinoma (1 paper, 2023). A carcinoma that arises from the lung and is characterized by the presence of malignant glandular epithelial cells. "We explored the expression of PHF23 in tumors using TCGA and found that PHF23 mRNA was highly expressed in various tumor tissues, including lung adenocarcinoma and lung squamous carcinoma tissues." (PMID 37626047, 2023).
tuberculosis (1 paper, 2025). A chronic, recurrent infection caused by the bacterium Mycobacterium tuberculosis. "PHF23-AF (which replaces the first exon of the PHF23 gene) is a selective splicing event related to the prognosis of tuberculosis, and a decrease in its splicing ratio (PSI value) is associated with a poor prognosis." (PMID 41268576, 2025). "The splicing variation of PHF23-AF will affect the proportion of PHF23 protein isoforms, which may thus influence its regulatory effect on autophagy and further affect the progression of tuberculosis." (PMID 41268576, 2025). "Therefore, PHF23 may hinder the clearance of M. tuberculosis by inhibiting autophagy, leading to an increase in bacterial load and ultimately resulting in a poor prognosis for patients with tuberculosis." (PMID 41268576, 2025).
tumor (10 papers, 2017 to 2026). "Plant homologous structural domain finger protein 23 (PHF23) promotes tumor proliferation and migration, yet enhances cisplatin/docetaxel sensitivity by facilitating DNA damage repair." (PMID 41306527, 2025). "PHF23 demonstrates equally complex tumor-suppressive functions, primarily mediated through epigenetic regulatory mechanisms." (PMID 41268576, 2025). "Relevant studies have confirmed that PHF23 is identified as a 17p tumor suppressor gene (TSG), which exerts its tumor-suppressive function through its association with epigenetic regulatory mechanisms." (PMID 41268576, 2025). "Multiple studies demonstrate that PHF23 contributes to tumor development through diverse pathophysiological mechanisms." (PMID 41268576, 2025). "PHF23’s role in tumorigenesis has drawn significant research interest due to its dual tumor-promoting and tumor-suppressing functions." (PMID 41268576, 2025). "PHF23 overexpression correlates with enhanced cell proliferation, migration, chemoresistance, and DNA repair capacity - all key factors promoting tumor formation." (PMID 41268576, 2025). "The expression of PHF23 is positively correlated with the degree of tumor differentiation, tumor size, lymph node metastasis, and TNM staging." (PMID 41268576, 2025). "Correlation analysis with clinicopathological factors revealed that PHF23 expression was positively correlated with tumor differentiation (P = 0.011), tumor size (P = 0.002), lymph node metastasis (P = 0.005), and TMN stage (P = 0.009)." (PMID 37626047, 2023). "We further investigated the biological role of PHF23 in vivo, using the H1299 cell-derived xenograft tumor model for validation." (PMID 37626047, 2023). "Notably, the role of PHF23 in promoting tumor metastasis is similar to the function of heparanase in tumor invasion." (PMID 41268576, 2025). "PHF23 demonstrates potential tumor-suppressive functions in BC." (PMID 41268576, 2025). "Multiple tumor suppressor genes like PHF23, EIF5A, KCTD11, MAP2K4 and ALOX15B, have been reported to promote tumorigenesis when lost, indicating that gene expression regulation, signal transduction, arachidonate lipoxygenase and other cellular pathways are altered with the loss of chromosome 17p." (PMID 36750552, 2023). "Therefore, PHF23 can promote tumor cell proliferation and chemoresistance through activation of the ERK signaling pathway in vivo." (PMID 37626047, 2023). "A recent study revealed an epigenetic regulatory mechanism involving a new tumor suppressor gene, PHF23, which may contribute to the pathology of 17p-deleted cancers." (PMID 35383271, 2022). "Moreover, PHF23 significantly counteracted the tumor suppressive effect of cisplatin." (PMID 37626047, 2023). "PHF23 exerts strong oncogenic effects in NSCLC and drives tumor progression through multiple pathways." (PMID 41268576, 2025). "Through its PHD domain, PHF23 interacts with Alpha-actinin-4 (ACTN4), subsequently activating the ERK signaling pathway to stimulate tumor cell proliferation and metastasis." (PMID 41268576, 2025). "In this study, we revealed that PHF23 is mainly localized in the nucleus, and its expression level correlated with various clinicopathological parameters of NSCLC, including tumor size, lymph node metastasis, and TNM stages." (PMID 37626047, 2023). "In human tumor cell lines, PHF23 (PHD finger protein 23) with a PHD-like zinc finger domain interacted with the E3 ubiquitin ligase LRSAM1 (leucine-rich repeat and sterile α motif-containing 1), which negatively regulates ubiquitin-dependent autophagy." (PMID 36036638, 2022). "PHF23 cooperates with chromodomain helicase DNA-binding protein (CHD) subfamily members, participating in chromatin remodeling and gene expression regulation, while displaying multifaceted roles in tumor development." (PMID 41268576, 2025).
tumor (continued). "It has been recently reported that H3K4me3 reader PHF23 interacts with SIN3-HDAC complex to mediate a synergistic action of H3K4me3 and H3K27ac on inhibition of the deacetylation activity of SIN3-HDAC complex, resulting in activation of tumor suppressor genes." (PMID 37581938, 2023). "Overexpression of PHF23 resulted in a significant increase in both the volume and weight of xenograft tumors in vivo, whereas the PHF23-mediated promotional effect on tumor growth was abolished in the absence of the PHD." (PMID 37626047, 2023).
cancer (5 papers, 2022 to 2025). A tumor composed of atypical neoplastic, often pleomorphic cells that invade other tissues. "In B-cell lymphoma, which is a common cancer associated with 17p deletion, PHF23 has been found to potentially suppress its development and progression." (PMID 41268576, 2025). "It is noteworthy that although PHF23 haploinsufficiency is only one of hundreds of genes implicated in human cancers with 17p deletions, it is nevertheless required for these cancers’ maintenance." (PMID 41268576, 2025). "Besides this PHF23-regulated epigenetic mechanism, metabolic alterations have been observed in cancers with del(17p)." (PMID 36750552, 2023). "The Cancer Genome Atlas data mining, NCBI/GEO data mining, and western blotting analysis were employed to characterize the expression of PHF23 in NSCLC cell lines and tissues." (PMID 37626047, 2023). "Therefore, further investigation into the specific molecular mechanisms by which PHF23 functions as a TSG is of significant importance for the treatment and prevention of cancer." (PMID 41268576, 2025). "Both PHF23 and TP53RK mRNA downregulation was confirmed by RNA-seq analysis in the blood of enitociclib-treated patients and further studies are warranted to uncover the utility of enitociclib to downregulate these potential cancer targets." (PMID 37882668, 2023).
psychiatric disorder (1 paper, 2025). A disorder characterized by behavioral and/or psychological abnormalities, often accompanied by physical symptoms. "Several genes—including ATP6V1B2, FBXO7, PHF23, and WDR6—consistently emerged as risk factors in multiple conditions, suggesting that dysregulation of autophagy-related or immune-modulatory pathways may contribute broadly to the development of inflammatory and psychiatric disorders." (PMID 41595424, 2025).
PHF23 also shares sentences with these, for which no sentence is quoted: acute lymphoblastic leukemia (3 papers); B-cell acute lymphoblastic leukemia (1); lymph node metastasis (1).